CD4 (CD4 molecule)
Diseases named in the same sentence as CD4 in open-access papers (continued):
Sharing a sentence is not in itself a finding about the gene and the disease.
influenza (continued). "Finally, to what degree do the different CD4 T cell subsets and their potentially unique specificities regulate each other’s function and how much do these interactions confound efforts to quantify the contribution of CD4 T cells to influenza immunity?" (PMID 26834750, 2016). "Lung CD4 TRM cells have recently been characterized following influenza infection." (PMID 27148257, 2016). "Many functions of influenza-specific CD4 T cells have been described." (PMID 26834750, 2016). "The preceding findings regarding the link between HA specificity of CD4 T cells and antibody responses are of particular importance when considering the ability of circulating CD4 memory to provide help for protection against novel and potentially pandemic strains of influenza." (PMID 26834750, 2016). "Importantly, at late time points post influenza infection, a population of antigen-specific IL-6Rα+IL-7R+ CD4+ T cells emerges coincident with a decline in the effector population." (PMID 26743592, 2016). "Together, our findings provide insights about T-cell responses to the influenza vaccine and illustrate the general utility of this novel combinatorial approach to efficiently characterize CD4+ T-cell ex vivo from limited samples in a variety of different contexts." (PMID 27571776, 2016). "Together, these complexities in the influenza-specific CD4 T cell repertoire constitute a formidable obstacle to predicting protective immune response to potentially pandemic strains of influenza and in devising optimal vaccine strategies to potentiate these responses." (PMID 26834750, 2016). "Furthermore, a model including the influenza vaccine specific activated CD4+ CD40L+ T cells together with age and NSSN gave poor predictive results for protection against the California strain." (PMID 26954292, 2016). "However, recent studies have shown an important role for CD4 help during CD8 priming in the formation of CD8 resident memory T (TRM) cells in lung airways during influenza infection." (PMID 27148257, 2016). "Also, does antigen specificity influence the ability of CD4 T cells to convey the other functions of CD4 T cells in protective immunity to influenza?" (PMID 26834750, 2016). "In addition to virus-specific CD4+ T cells and CD8+ T cells responses, FoxP3+ CD4+ regulatory T cells (Tregs) and T helper 17 cells (Th17) are also induced during influenza infection." (PMID 26407325, 2015). "Interestingly, LAIV is the only vaccine that contains influenza-specific CD4 (+), CD8 (+), and γδ T cells for highly conserved influenza peptides." (PMID 28316730, 2015). "Importantly, a functional memory CD8+ and CD4+ T cell pools capable of eliciting recall responses to the same extent as following the normal, ‘uninterrupted’, influenza infection, was established during this drug-reduced effector phase." (PMID 26086392, 2015). "Influenza virosomes could be an excellent candidate platform for a cross-protective influenza vaccine, as it is an effective peptide delivery system and a natural carrier of CD4+ T-cell and B-cell epitopes." (PMID 25344321, 2015). "Therefore, we set up a ‘B cell helpless system’ using OT-II TCR transgenic mice as recipients because they have a fixed non-influenza-specific CD4 T cell compartment that cannot provide help to GC B cells during the infection." (PMID 25569154, 2015). "Our univariable analysis found consistent (although weak) correlations between the expression levels of CD28 on both CD8+ and CD4+ T cells and influenza vaccine-induced memory-like IgG B cell ELISPOT response measured at different timepoints, but not antibody titers." (PMID 25816015, 2015). "IL-6 is involved in the development of influenza-specific memory CD4 T cells." (PMID 26282854, 2015).
influenza (continued). "Recent reports have suggested the importance of memory CD4+ T cells in influenza infection, as a result of their synergistic helper functions with B or T cells, as well as their contribution to the elimination of escape viral mutants in absence of B cells or CD8+ T cells." (PMID 25140692, 2014). "Thus, we compared the effects of developmental TCDD exposure on CD4+ T-cell–dependent and independent influenza-specific antibody levels, and on CD4+ T-cell–dependent B-cell differentiation." (PMID 25051576, 2014). "Thus the cytokine patterns expressed by CD4 T cells, even in the Th1-dominated response to influenza, can be determined by a combined effect of two mechanisms, short-term variability in cytokine expression, and semi-stable subset differentiation." (PMID 24788814, 2014). "Therefore, although SOCS1−/−IFN-γ−/− mice exhibited increased CD4+ T cell and influenza-specific antibody responses, these animals were competent in CD4+ T cell-independent resolution of influenza infection." (PMID 25500584, 2014). "The human CD4 memory T cell response to influenza can be explained by two types of diversity." (PMID 24788814, 2014). "This positive effect of AS03 on the CD4+ T-cell response to influenza vaccine strains in older adults could confer benefit in protection against clinical influenza disease in this population." (PMID 25078387, 2014). "Furthermore, depletion of CD4+ T cells prior to influenza challenge results in a dramatic drop of Ab titres, accompanied by only a small delay in virus elimination, driven by the remaining CD8+ T cell response." (PMID 24971078, 2014). "Thus, IL-10 becomes induced in IFN-γ+CD4+ T cells during influenza by IL-27, in part mediated via STAT4." (PMID 24809349, 2014). "They showed that, in the absence of antibody responses, pre-existing CD4+ T cells responding to influenza internal proteins were associated with less severe illness and lower virus shedding." (PMID 24795718, 2014). "This positive effect of AS03 Adjuvant System on the CD4+ T-cell response to influenza vaccine strains in older adults could confer benefit in protection against clinical influenza disease in this population." (PMID 25078387, 2014). "Interestingly, influenza-specific lung CD4 TRM protected from morbidity of infection while also mediating rapid viral clearance, and carried out these functions in situ without extensive proliferative expansion or migration to other sites." (PMID 25071787, 2014). "Moreover, lung CD4 TRM generated following influenza infection were maintained longterm and were unperturbed in the presence of inhibitors of lymphoid egress and inducers of lymphopenia." (PMID 25071787, 2014). "Conversely, CD4+ T cell-mediated viral escape in influenza has received considerably less attention and the selection of CD4+ T cell escape peptide variants has not currently been demonstrated, either within an individual or across a population." (PMID 24971078, 2014). "In the absence of detectable humoral immunity, evidence from human and non-human models demonstrated the protective role of epitope-specific preexisting CD4+ T-cell immunity in attenuating the influenza disease by influencing the transmission dynamics of the pathogen." (PMID 24609014, 2014). "Thus, there was less of an effect of ageing on the influenza-specific CD4 T cell repertoire than we had previously shown for the CD8 T cell repertoire." (PMID 24999367, 2014). "While it is known that memory CD4+ T cells can cooperate with naïve B or CD8+ T cells in the context of influenza infection, it is unknown whether a similar cooperativity occurs with influenza virus-specific CD8+ T cells." (PMID 23516357, 2013). "However, influenza vaccines are already licenced which use adjuvants which promote strong CD4+ T cell responses and have been shown to be safe." (PMID 24086140, 2013). "Both CD8+ CTL and CD4+ T-cells gave protection against influenza challenge." (PMID 26056568, 2013).
influenza (continued). "Moreover, DRB1*04∶01 tetramers loaded with HA 306–318 have demonstrated increased frequency of CD4+ T Cells-restricted to HA 306–318 following influenza vaccination." (PMID 23951151, 2013). "In addition to the provision of CD4 T cell help for B cell differentiation, both CD4 effector and memory T cells appear to have multifaceted roles in the protective responses to influenza infection." (PMID 23890405, 2013). "Although CD4 T cells are important for generating NAb, there is some debate as to whether CD4 T cells and antibodies correlate following influenza vaccination." (PMID 24155927, 2013). "However, the CA/09ni vdiff pool, representing the peptides least likely to cross-react with epitopes in previous influenza strains, revealed a strongly enhanced response biased towards IFNγ−IL-2+TNFα+ CD4 T cells after PCR-confirmed CA/09 infection." (PMID 23526940, 2013). "M2e-based protection against influenza can be mediated by M2e-specific antibodies but might also depend on M2e-specific CD4 T cells." (PMID 23527091, 2013). "In aging HIV-infected and uninfected women, activated CD4 and pTfh cells may compromise influenza vaccine-induced antibody response, for which a mechanism of TNFα-mediated impairment of pTfh-induced IL-21 secretion is postulated." (PMID 24236161, 2013). "A recent human challenge study with influenza demonstrated that pre-existing CD4+ T-cell responses to conserved NP and matrix protein could reduce severe illness in the absence of specific antibodies." (PMID 23555741, 2013). "The importance of CD4+ T cell responses in influenza infection is well documented." (PMID 23641949, 2013). "Indeed, SIV+ CD4-low mangabeys are able to generate recall antibody responses to vaccination against Influenza and DN T cells have the potential to assist in facilitating this helper T cell function." (PMID 23825945, 2013). "In addition effector CD4+ T cells have been shown utilize a perforin-dependent cytolytic mechanism to fight influenza infection and control influenza titers in a perforin-dependent manner." (PMID 24204639, 2013). "Furthermore, vaccination with the influenza DNA vaccine coding NP helped to induce high levels of secretion of CD4+ Th1, and to increase the levels of interferon-γ and interleukin-20." (PMID 26056568, 2013). "Although TIV may be effective in healthy young individuals, differences in the vaccine-induced CD4 T cell response in aged individuals may provide clues to help optimize influenza immunity in this vulnerable population." (PMID 24155927, 2013). "Human memory CD4+ T cells specific for conserved influenza proteins have been demonstrated to be cross-subtype responsive and we hypothesized that immunization with conserved RV proteins might induce similarly cross-reactive cells." (PMID 24086140, 2013). "For example, we demonstrated that cross-reactive influenza-specific memory CD4+ T cells were present prior to the introduction of pandemic H1N1, and have postulated that they play an important role in reducing the disease severity of pandemic H1N1 infection in humans." (PMID 23251663, 2012). "We evaluated the proliferative capacity of CD4+ T-cells in response to influenza antigens." (PMID 22715399, 2012). "We speculate, therefore, that the influenza-specific proliferative CD4+ T-cell responses are impaired earlier than effector responses during HIV infection." (PMID 22715399, 2012). "Based on our previous IFN-γ-ELISPOT analyses, influenza M1-specific CD4+ T-cell responses and the HLA-A*0201-restricted influenza M1 CD8+ T-cell epitope are present in frequencies between 1/10,000 and 1/1,000, which is about the frequency of tumor-specific T cells after vaccination." (PMID 22491788, 2012). "The antibody response to influenza infection is largely dependent on CD4 T cell help for B cells." (PMID 22457834, 2012).
influenza (continued). "Our results demonstrated an influenza-specific recall response in the CD4+CD8− (naïve), the CD4−CD8+ (CTL) and the CD4+CD8+ (Thelper) cells of pigs vaccinated with the adjuvanted split vaccine, but only in the CD4+CD8+ (Thelper) cells of pigs vaccinated with the non-adjuvanted whole vaccine." (PMID 22427834, 2012). "We next tested whether human CD4 T cells expressed AR during antigen/APC stimulation in response to influenza peptides, allergens or tetanus antigens to stimulate Type 1, Type 2 and Thpp-biased recall responses, respectively." (PMID 22720031, 2012). "Furthermore, high levels of pre-existing CD4+ T cell memory correlate with reduced viral loads and clinical scores in a human influenza challenge study, highlighting the importance of T cell memory in viral infection." (PMID 23230439, 2012). "Therefore, the optimal CD4+ T cell polarisation in terms of influenza vaccination needs to be further investigated." (PMID 22069479, 2011). "The c-di-GMP adjuvanted virosomal H5N1 vaccine induced homologous (H5N1) and hetero-subtypic (pH1N1) influenza-specific CD4+ Th1 cells and significantly higher (p<0.01) frequencies of CD4+ Th1 cells were produced after mucosal (IN and SL) than IM administration." (PMID 22069479, 2011). "Thus, although the c-di-GMP adjuvanted vaccine induced CD4+ Th1 cell responses when administered IM, the frequencies of homologous and hetero-subtype influenza-specific CD4+ Th1 cells were significantly higher upon IN and SL administration." (PMID 22069479, 2011). "Given the recent identification of a highly functional VLA-1+ tissue-memory CD4+ T cell subset, and the importance of having memory T cells in the airways in models of secondary influenza challenge, we sought to better understand the in vivo contributions and behavior of these local memory T cells." (PMID 21647373, 2011). "CD4+ T-cell responses are also essential for a fully developed CD8+ T-cell response to influenza." (PMID 22039539, 2011). "Also in this group, a pronounced rise in influenza-specific CD4- and CD8 T-cells was observed after challenge with swine influenza virus." (PMID 20808939, 2010). "Our work is the first demonstration that the immunization route in humans affects the magnitude and quality of CD8 T cell responses as well as the intrinsic quality of cytokine-producing CD4 effector cells after TC and IM vaccination with a seasonal influenza vaccine." (PMID 20520820, 2010). "We found that smoke reduced the influenza-associated induction of lung mRNA encoding MIG at d10 and of IP-10 at d3, which could explain how smoke modified the kinetic profiles of CD4+ and CD8+ T cells." (PMID 18627612, 2008). "CD4+ T cells are implicated in mucus hypersecretion in smokers and are important but not essential for clearance of influenza in mice." (PMID 18627612, 2008). "However, at d10, smoke and influenza mice had many more CD4+ and CD8+ T cells in BALF, than influenza alone mice." (PMID 18627612, 2008). "To confirm that virus-specific Treg activity was more readily detectable in the absence of IL6, we stimulated co-cultures of CD4+CD25− cells (obtained from influenza-infected WT mice) and CD4+CD25+ cells purified from either influenza-infected WT or IL-6−/− mice with APCs infected with the virus." (PMID 18389078, 2008). "However, the stimulation with the seasonal influenza vaccine preparation induced the production of IFN-γ by CD4 effector T cells (panel B: 3.2% of IFN-γ+ CD4+ T cells)." (PMID 18258091, 2008). "Analysis of the role of complement in the enhanced injury and inflammation in the lungs of influenza-infected Cd59a–/– mice revealed that increased neutrophil infiltration was dependent on complement activation whilst enhancement of the CD4+ T cell response was complement-independent." (PMID 17429844, 2007).
influenza (continued). "Observed decreases in influenza-related hospitalizations with the advent of effective antiretroviral therapies (ART) suggest that the severity of seasonal influenza may be lower among patients with higher CD4 cell counts." (PMID 40260188, 2025). "In influenza cases, a rapid decrease in CD4 T lymphocytes may lead to the development of PCP." (PMID 40260188, 2025). "Similarly, DHODH inhibition by IMU-838 reduced CD4+ T cell responses to flu antigens." (PMID 40706797, 2025). "While natural influenza infection and a number of novel vaccine strategies have been shown to induce increased protection and broadly neutralizing antibodies, the mechanisms or involvement of CD4+ T cells in GC reaction to generate those broadly neutralizing antibodies were not described." (PMID 39283916, 2024). "This is not surprising as a clinical trial on a plant-derived VLP displaying influenza HA antigen has already demonstrated the VLP vaccine could elicit a higher CD4+ T cell response as well as a comparable CD8+ T cell response than a commercial inactivated vaccine." (PMID 39081325, 2024). "As virus- and vaccine-induced lung-resident CD4+ TRM cells have been shown to mediate protection from influenza infection, it is important to understand how heterologous infection or immunization priming of CD4+ TRM cells and resultant subsets of TRM cells could enhance localized immune responses." (PMID 39283916, 2024). "In addition, IMP321 has been described to enhance the response of Th1 influenza-specific CD4+ cells by increasing the secretion of IFN-γ, the prototypical Th1 effector cytokine, TNF-α, an inflammatory cytokine, and IL-2, which is involved in the development of memory T cells." (PMID 36680187, 2023). "In each of the models, CD4+ T cells are recruited to the site of inflammation, and each type of infection is dominated by the corresponding TH cell subset, in numbers and proportions; Influenza by TH1 cells (IFNγ), N. brasiliensis by TH2 cells (IL-4, IL-13), and A. fumigatus by TH17 cells (IL-17)." (PMID 37696824, 2023). "The NT1-associated variants may thus affect disease predisposition by increasing influenza viral (as opposed to bacterial) uptake and antigen presentation to CD4+ T cells." (PMID 37188663, 2023). "In larger DNA viruses, such as vaccinia, it is well established that T cell help is specific only for the same protein; on the other hand, it was shown that CD4+ helper T cells primed to internal components of influenza could provide help to HA-specific B cells to generate HA-specific Abs." (PMID 37711622, 2023). "Taken together, these findings suggest that NT1-associated variants may affect disease predisposition by increasing influenza viral (as opposed to bacterial) uptake and antigen presentation to CD4+ T cells, although additional mechanisms could be involved." (PMID 37188663, 2023). "However, a small subset of CD4+ T-cells has also direct cytolytic capacities via granzyme B and perforin dependent mechanisms and represents an important antiviral effector of cell-mediated immunity against influenza infection." (PMID 36052083, 2022). "Additionally, diminished CD4/CD8 ratios correlate with poor antibody titres against influenza." (PMID 36077216, 2022). "In summary, if the A/H1N1pdm09 viral preexposure suggested by some pharmaco-epidemiological studies is confirmed, a plausible hypothesis is that the ‘priming’ of the cross-reactive CD4+ T-cell response by natural infection was further activated following pandemic influenza vaccination." (PMID 36311717, 2022). "Indeed, one study from the Sant group utilized a nanoparticle vaccine linked to the influenza nucleoprotein (NP) which was administered intranasally, and found to elicit persistent and polyfunctional influenza specific CD4+ Trm responses in the lung that protected from severe disease in mice." (PMID 36275668, 2022).